CRP (C-reactive protein)
Diseases named in the same sentence as CRP in open-access papers (continued):
Sharing a sentence is not in itself a finding about the gene and the disease.
heart failure (continued). "Interestingly, we found that proinflammatory cytokine TNF-α positively correlated with high sensitivity C-reactive protein in patients with advanced heart failure undergoing heart transplantation." (PMID 37745103, 2023). "Moreover, the ROC diagnostic analysis showed that CRP (>5 mg/L) and NLR (>3.5) had significant predictive ability for early postoperative cardiac insufficiency and death within 30 days after surgery, respectively." (PMID 37063874, 2023). "Furthermore, LYC has been observed to reduce C‐reactive protein (CRP) levels among patients with heart failure as well as healthy individuals." (PMID 37070131, 2023). "In the following, various studies investigated the prognostic values of elevated CRP levels with the incidence and features of more severe heart failure; several large studies have shown that CRP predicts morbidity and mortality in patients with established HF." (PMID 36882679, 2023). "CRP and IL-6 are common inflammatory mediators that are mainly produced by activated macrophages, whereas galectin-3 is a newly discovered inflammatory marker of heart failure and is produced by macrophages." (PMID 35356068, 2022). "The patient presented with concomitant cardiac insufficiency, hepatic and renal failure, delirium with high C-reactive protein levels and the patient’s response to glucocorticoids, and exclusion of cerebrovascular accident and severe infection, resulting in a final diagnosis of CRS." (PMID 36626467, 2022). "In addition, the phase II VCU-ART and VCU-ART2 trials using anakinra (a IL-1 receptor blocker) showed a reduction in CRP levels and a reduced incidence of heart failure after 3 months in STEMI patients." (PMID 35864531, 2022). "In the group of inflammatory biomarkers of heart failure are some traditional biomarkers, such as C-reactive protein (CRP) and high-sensitivity C-reactive protein (hs-CRP), tumor necrosis factor-alpha (TNF-α), interleukin-6 (IL-6), as well as some new biomarkers." (PMID 35626917, 2022). "The cardio-inflammatory phenotype of heart failure is of particular interest since markers such as CRP, a soluble isoform of IL-1 receptor-like 1 (also known as sST2), have been seen to be increased in the phenotype, indicating a vital role in the disease process." (PMID 36649041, 2022). "The addition of heart failure was associated with an additional increase in the level of C-reactive protein, TNF-α, and IL-6 in the blood, regardless of patients’ sex." (PMID 35997392, 2022). "Therefore, the positive correlation between the IVC/AO ratio and CRP is reasonable, as CRP also increases in heart failure patients." (PMID 36059561, 2022). "The aim of C-DOS was to investigate whether digoxin is capable of lowering CRP levels in patients with heart failure and a left ventricular ejection fraction below 40%." (PMID 35407370, 2022). "It has been reported that the levels of IL-6, CRP, and TNF-α are important indicators of MI-related cardiac complications, and these inflammatory cytokines have been reported to be closely associated with the occurrence of heart failure." (PMID 34123595, 2021). "Mendelian randomization (MR) estimates of CRP and fibrinogen with heart failure." (PMID 34881299, 2021). "The present study determined that CRP ≥ 6.5 mg/L at discharge was associated with an excess risk for paravalvular abscess within 1 year, but not with risk of heart failure hospitalization." (PMID 34434979, 2021). "Notably, canakinumab also reduced heart failure hospitalisation and heart failure-related mortality by 23% in patients who achieved a CRP level of <2 mg/l." (PMID 33861346, 2021). "The elder age, certain comorbidities (cancer, heart failure, chronic renal failure), dyspnea, lower levels of oxygen saturation and hematocrit, higher levels of C-reactive protein, aspartate aminotransferase and ferritin were independent risk factors for mortality." (PMID 33546639, 2021).
heart failure (continued). "In addition, gender, serum CRP level, albumin level, neutrophil count, PNI score, NSCLC staging, platinum application, NLR, metastasis, surgery, heart failure, and KPS score were also associated with overall mortality." (PMID 32939184, 2020). "In addition, increased heart-type fatty acid–binding protein and C-reactive protein (CRP) levels were reported to be possibly predictive of heart failure or mortality during the follow-up of AMI patients." (PMID 32903533, 2020). "In addition, sex, serum CRP level, albumin level, neutrophil count, PNI score, NSCLC stage, application of platinum, NLR, metastasis, surgery, heart failure, KPS score, and miR-1231 levels were associated with overall mortality." (PMID 32939184, 2020). "Finally, we identified the correlativity between key gene expressions and clinical and prognosis factors, including the EF value, heart failure, CRP value, and BMI value by logistic regressive analysis." (PMID 33224271, 2020). "Considering the possible role of oxidative stress and inflammation in the initiation and progression of PPCM, various inflammatory biomarkers including C-reactive protein (CRP), TNF-alpha and interleukin-6 have been studied and demonstrated to be associated with this unique form of heart failure." (PMID 31092205, 2019). "One recent study has shown that hs-CRP is an independent predictor of heart failure in T2DM." (PMID 31073335, 2019). "We hypothesize that canine heart failure patients have elevated markers of systemic inflammation (CRP, WBC and NEUT)." (PMID 29573742, 2018). "The weak correlationship between the BNP and CRP levels in cancer patients in the present study might suggest the inclusion of hidden heart failure." (PMID 28570595, 2017). "Similarly, IL-6 and C-reactive protein were reduced following Hatha yoga intervention in heart failure patients, which represent another clinical population with a high baseline inflammatory burden, compared to controls." (PMID 28694775, 2017). "The pleural CRP levels significantly differentiated the four groups (p < 0.001) with the following means: parapneumonic effusion, 5.38 ± 4.85 mg/dL; lung transplant, 2.77 ± 2.66 mg/dL; malignancy, 1.19 ± 1.51 mg/dL; and heart failure, 0.57 ± 0.81 mg/dL." (PMID 27194820, 2016). "It was shown that CCC, at the dosage of 666.7 mg/kg per day, could decrease the blood lipids and C-reactive protein significantly and improves the symptoms of cardiac insufficiency." (PMID 26539229, 2015). "Circulating N-terminal pro-B-type natriuretic peptide (NT pro-BNP), high- sensitivity C-reactive protein (hs-CRP) and big endothelin (big-ET) have been shown to be increased in heart failure and to contribute to both hemodynamic deterioration and cardiovascular remodeling." (PMID 24885051, 2014). "Elevated levels of CRP have been observed in patients with HF, and activation of the immune response may play a role in heart failure through modifications in the renin-angiotensin-aldosterone and sympathetic systems." (PMID 24885051, 2014). "Elevated levels of biomarkers of systemic inflammation, immune function, and ventricular remodeling, such as C-reactive protein (CRP), tumor necrosis factor (TNF), and endothelin-1, also have been associated with morbidity and mortality among heart failure patients." (PMID 22588803, 2012). "Patients in the first tertile, with the lowest pH levels (pH ≤7.39), more often were current smokers, more often showed signs of decompensated heart failure, had higher respiration rates, had lower C-reactive protein levels, and presented with lower oxygen saturation at presentation." (PMID 21663600, 2011). "Hopefully clinicians may consider the initial WBC count and CRP as almost equally powerful measures of possible left ventricular systolic dysfunction occurence, that may lead to heart failure." (PMID 19503842, 2009).
heart failure (continued). "Likewise, the favorable impact of semaglutide on inflammatory markers such as CRP and NT-proBNP levels might provide further insight into the potential benefit of semaglutide in patients with heart failure with preserved ejection fraction (HFpEF)." (PMID 39753963, 2025). "Another MR study exploring the link between inflammatory markers and heart failure (HF) has yielded a different result, concluding that genetically predicted CRP was not likely to cause HF and that there was only weak evidence of a causal effect between the two." (PMID 36882679, 2023). "Moreover, SIRI could better reflect the long-term inflammatory change state of heart failure than a single CRP." (PMID 35911534, 2022). "Reactive oxygen species activate nuclear factor-kappa B, which leads to increased production of C-reactive protein, tumor necrosis factor-α, and interleukin-6, along with adhesion molecules such as E selectin, CD15, and CD32 that can cause endothelial damage, CHD, heart failure." (PMID 35287580, 2022). "However, in chronic SCZ patients, the expression levels of CRP could be significantly increased, which has been shown to play an essential role in the development of heart failure after MI." (PMID 34149793, 2021). "However, in the present study the risk of rehospitalization for heart failure at discharge was not significantly higher in the high-CRP (≥6.5 mg/L) relative to the low-CRP group." (PMID 34434979, 2021). "Similarly, CRP was 90% sensitive and 25.53% specific for heart failure." (PMID 32181077, 2020). "Compared to control group, six-minute walking test (6-MWT) distance was longer, and Minnesota Living with Heart Failure Questionnaire (MLHFQ) score and levels of inflammatory markers (IL-6, TNF-α, and hs-CRP) were lower in the study group (all p < 0.05)." (PMID 42058421, 2026). "There is a large body of literature evaluating CRP as a prognostic biomarker in DCM and heart failure populations." (PMID 41596517, 2026). "Variables were selected from 13 candidate factors (age, mechanical ventilation, nutritional status, comorbid respiratory failure, comorbid heart failure, pulmonary rales, pulmonary rhonchi, PLT, CRP, PCT, IL-6, IgA, and IgM)." (PMID 41234411, 2025). "This meta-analysis confirms that systemic inflammation—reflected by elevated IL-6, hs-CRP, and NLR—is a strong and independent predictor of mortality and adverse outcomes in heart failure." (PMID 41375916, 2025). "Multiple randomized clinical trials and observational studies have shown that an omega-3 supplementation significantly reduces inflammatory biomarkers such as C-reactive protein (CRP), IL-6, and TNF-α in patients with CKD and heart failure." (PMID 40806569, 2025). "We compared the dynamics of inflammatory markers—CRP, ESR, and fibrinogen—between T0 (baseline) and T1 (6-month follow-up) using a multivariate analysis of variance (MANOVA) across the three heart failure phenotypes (HFrEF, HFmrEF, and HFpEF)." (PMID 40134442, 2025). "Since then, multiple studies have emphasized the prognostic relevance of inflammatory markers such as C-reactive protein (CRP), tumor necrosis factor-alpha (TNF-α), and interleukin-6 (IL-6) in heart failure." (PMID 40869365, 2025). "Studies suggest that omega-3 supplementation effectively lowers circulating levels of inflammatory cytokines, particularly in patients with heart failure (HF), by reducing TNF-α, IL-6, and C-reactive protein (CRP) levels." (PMID 40427653, 2025). "Depressed persons had higher levels of CRP, higher blood pressure, a worse LDL/HDL ratio, and peripheral artery disease, heart failure, and COPD were more frequent." (PMID 38459472, 2024). "Patients with C-reactive protein ≥ 2 mg/L had higher healthcare resource utilization and a higher rate of MACE, heart failure, and death." (PMID 39211962, 2024). "CRP level >5 mg/L and NLR >3.5 can effectively predict postoperative heart failure and death within 30 days after surgery, respectively." (PMID 37063874, 2023).
heart failure (continued). "A nomogram model was constructed based on 11 risk prediction indicators, including age, NIHSS score, dysphagia, atrial fibrillation, cardiac insufficiency, renal insufficiency, hepatic insufficiency, FBG, CRP, NEUT% and prealbumin." (PMID 38034684, 2023). "CRP, white cell count and creatinine were significantly higher for patients with MACE and heart failure, malignancy and chronic kidney disease (CKD) were more prevalent in patients with MACE compared with patients without MACE." (PMID 37955026, 2023). "CRP level >5 mg/L and NLR >3.5 showed relatively high predictive power in terms of postoperative cardiac insufficiency and death within 30 days after surgery, respectively." (PMID 37063874, 2023). "Evidence from observational cohort studies suggests that elevated CRP is a risk factor for the incidence of heart failure independent of conventional risk factors and other biomarkers, indicating that these inflammation biomarkers may play etiological roles in HF." (PMID 36882679, 2023). "For instance, the C-reactive protein (CRP) has been considered as a useful biomarker to predict cardiac death, AMI, and heart failure." (PMID 36291959, 2022). "While CRP has been proven to be a useful biomarker for predicting many adverse outcomes in STEMI patients, the CRP level changes over time—CRP velocity (CRPv), may be a more sensitive biomarker for identifying patients’ inflammatory state and risk of developing subsequent heart failure." (PMID 35054095, 2022). "This index included the following variables: NYHA III and IV heart failure, COPD, generalized atherosclerosis, NIHHS scale, and CRP/hemoglobin ratio." (PMID 36430028, 2022). "The extra risk of accelerated CVD may be a result of increased myeloperoxidase and CRP protein level, together with decreased vitamin D. Increased NT-proBNP may be evidence of early impairment of the myocardial muscle and a marker of early development of heart failure." (PMID 36012972, 2022). "Age, BMI, systolic or diastolic blood pressure, LVEF, NYHA class, history of heart failure, prescription of β-blockers or ACEI, hemoglobin, leukocytes, eGFR, blood urea nitrogen, CRP, and NT-pro BNP." (PMID 36204571, 2022). "In agreement, some of the evidence included in this review show that enhanced EAT correlates with proinflammatory markers such as C1q, C-reactive protein and CTRP1 in patients with heart failure." (PMID 34671870, 2022). "This risk score model incorporating BMI, EF, serum creatinine, hemoglobin, CRP, and NLR, effectively evaluates patients’ severity classification of heart failure, closely related to MACE." (PMID 35647038, 2022). "It was suggested that NLR level should be explained with other inflammatory biomarker such as CRP/ALB and heart failure indicator to improve the ability of predicting mortality risk." (PMID 33746575, 2021). "In dogs with microembolization-induced heart failure, plasma levels of the cytokines TNF-α, IL-6, and c-reactive protein (CRP) were significantly elevated compared with normal baseline levels." (PMID 33001359, 2021). "Accordingly, NT-proBNP is a stronger indicator of cardiac dysfunction than CRP in the general population and in subjects with SCAD or heart failure." (PMID 33271910, 2020). "According to the age-adjusted analysis, heart failure, malignancy, kidney function parameters, and sodium, calcium, albumin, LDH, AST, CRP, ferritin, D-dimer, Hct, WBC and lymphocyte levels were associated with mortality." (PMID 32881976, 2020). "Specifically, patient 1 presented with heart failure and LVH, and TdP occurred during acute complete atrioventricular-block, in the presence of high CRP." (PMID 32477142, 2020). "Statins had also been reported to decrease levels of C-reactive protein, interleukin-6, TNF-α, improve left ventricular function among individuals with heart failure." (PMID 31627722, 2019). "Additionally, CRP may be an independent marker of improvement and readmission in heart failure." (PMID 29573742, 2018).
heart failure (continued). "The CRP concentration, WBC and NEUT were significantly increased in advanced-stage heart failure patients in comparison with compensated patients and healthy dogs, which indicate the presence of systemic inflammation." (PMID 29573742, 2018). "At baseline, only age, FPG, CRP, CAD types, GFR, history of heart failure, and treatment with percutaneous coronary intervention were different among MCP-1 tertiles." (PMID 25786118, 2015). "We used the markers troponin I, BNP and hs-CRP to serially evaluate for myocardial necrosis (troponin I), cardiac failure (BNP), or an inflammatory response (hs-CRP)." (PMID 25488804, 2015). "Similar to IL-6, a general inflammatory biomarker C-reactive protein (hsCRP) also correlated with poor DCM prognosis, heart failure and mitochondrion-mediated myocyte apoptosis." (PMID 25888309, 2015). "Biomarkers of heart failure, myocardial injury, and systemic inflammation status as Brain Natriuretic Peptide (BNP), high‐sensitivity Troponin I (hsTnI), and C‐reactive protein (CRP) were collected pre‐ and post‐procedure of PVI for symptomatic AF." (PMID 40207269, 2025). "Overall, using the values of NGAL, urea, creatinine, troponin, and CRP, it is possible to accurately predict the presence of heart failure (HF) without a history of kidney disease of cases." (PMID 40862100, 2025). "These patients remained at high risk of admission to MICU after multivariable adjustment for SOFA score, PaO2/FiO2 ratio, CKD, heart failure, chronic liver disease, WBC, Hgb, ALB, D-dimer, AST, and C-reactive protein (CRP) (SMAT4: OR 4.731, 95% CI 1.853–12.075; SMIT4: OR 6.449, 95% CI 2.422–17.170)." (PMID 41211659, 2025). "However, NIIS differs mechanistically in that it couples a pleiotropic cytokine upstream of CRP with the GNRI, which emphasises protein reserves highly pertinent to sarcopenic heart-failure phenotypes." (PMID 41473193, 2025). "The study demonstrated that colchicine significantly reduced the risk of ischemic cardiovascular events (including stroke and angina) and reduced CRP levels; however, it should be noted that the trial did not specifically investigate heart failure outcomes." (PMID 40710370, 2025). "Cardiac biomarkers such as troponins (cTnI and cTnT), creatine kinase MB (CK-MB), brain natriuretic peptide (BNP), and high-sensitivity C-reactive protein (hs-CRP) play a pivotal role in diagnosing acute coronary syndromes (ACS), heart failure, and other cardiovascular conditions." (PMID 40244022, 2025). "In this case, the patient’s main symptom was heart failure, and there was no fever during the consultation and hospitalization, but there was an increase in CRP, which is consistent with most case reports." (PMID 39600931, 2024). "Based on the data, the important variables associated with the occurrence of NOAF were selected: age, CAD, heart failure, WBC, neutrophils, neutrophil percentage, CRP, PCT, TNF-α, MPO, HOCl, CR, TNI, NT-proBNP, LDL-c, SOFA score, APACHE II score, LVEF, and LVFS." (PMID 39030470, 2024). "A similar study conducted primarily in patients with systolic HF across varying stages concluded that the levels of inflammation such as IL-6, CRP, adiponectin, endothelin, and TNF-a, and oxidative stress, such as isoprostane increased along with the severity of heart failure." (PMID 36938237, 2023). "Nevertheless, in 2019, a meta-analysis with 9,289 established heart failure patients reported that hs-CRP did not provide more prognostic information than strong outcome predictors such as NT-proBNP and high-sensitivity troponin T (hs-TnT)." (PMID 36882679, 2023). "Completed pilot clinical trials on the use of anakinra in patients with reperfused STEMI undergoing primary percutaneous coronary intervention showed that IL-1 blockade was safe and reduced C-reactive protein (CRP) levels at 72 h and the rate of new-onset cardiac failure after STEMI infarction." (PMID 37507935, 2023).